PRKXP1 (PRKX pseudogene 1)
Gene: Processed pseudogene on chromosome 15 (100,553,529 to 100,558,954, reverse strand). Ensembl gene ENSG00000259205.
Diseases named in the same sentence as PRKXP1 in open-access papers:
PRKXP1 is named in the same sentence as 3 diseases in open-access papers, as found by Europe PMC text mining. Sharing a sentence is not in itself a finding about the gene and the disease. The quoted sentences say what the papers report.
Alzheimer disease (1 paper, 2012). A progressive, neurodegenerative disease characterized by loss of function and death of nerve cells in several areas of the brain leading to loss of cognitive function such as memory and language. "Recently, PRKXP1, SST and TNCRNA (also known as NEAT1, listed second by information gain) were identified by Squillario and Barla as part of a 39 gene signature implicated in Alzheimer’s disease." (PMID 23066814, 2012).
Crohn disease (1 paper, 2022). A gastrointestinal disorder characterized by chronic inflammation involving all layers of the intestinal wall, noncaseating granulomas affecting the intestinal wall and regional lymph nodes, and transmural fibrosis. "Furthermore, PRKXP1 is located on chromosome 15 and CpGs in this region have previously been associated with Crohn's disease and intestinal inflammation, a disease which has previously been reported to be more prevalent in females." (PMID 35568878, 2022).
PRKXP1 also shares sentences with these, for which no sentence is quoted: intestinal inflammation (1 paper).